INS (insulin)
Diseases named in the same sentence as INS in open-access papers (continued):
Sharing a sentence is not in itself a finding about the gene and the disease.
Obesity (continued). "It is well known that insulin sensitivity in PCOS is affected not only in women with overweight or obesity, but also in those with normal weight." (PMID 36675485, 2023). "A metabolic profile reflecting a combination of risk factors associated with an increased risk of cancer (obesity, Western diet, low physical activity) may provide a growth-promoting environment for cells, particularly neoplastic cells, possibly through influences on insulin resistance." (PMID 37764684, 2023). "It is important to note that, unlike B2 cells, B1a and B1b cell subtypes are able to improve insulin sensitivity in diet-induced obesity with the secretion of IgM autoantibodies." (PMID 37372966, 2023). "Again, the stability of subgroups was confirmed through k-means clustering, with some overlap between the obesity- and age-related subgroup and the body fat-related and insulin-resistant subgroup." (PMID 37402743, 2023). "Research has demonstrated that adipocytes’ secretion of TNF-α can prompt the phosphorylation of IRS-1 serine and reduce GLUT-4 expression, resulting in disruptions in insulin-regulated glucose metabolism and the onset of obesity-related IR." (PMID 38045856, 2023). "These metabolites have extensive effects on energy metabolism, insulin sensitivity, and the onset of obesity and related metabolic disorders." (PMID 37512528, 2023). "Leptin (p < 0.001) and C-peptide (p = 0.009) concentrations were significantly increased, and insulin sensitivity decreased (p = 0.002) in the group with overweight-obesity compared to the underweight-normal weight group." (PMID 37029207, 2023). "The absence of JNK1 led to decreased adiposity, significantly improved insulin sensitivity, and enhanced insulin receptor signaling capacity in dietary and genetic (ob/ob) models of mouse obesity." (PMID 36984693, 2023). "Our results show that, in individuals with obesity, in addition to a decreased insulin sensitivity and reduced β-cell function, a substantial decline in β-cell mass is also necessary for the emergence of overt T2D." (PMID 38026205, 2023). "While ICE does not consistently lower body weight or fat mass, there does seem to be evidence for ICE as a positive modulator of the metabolic consequences of obesity, such as glucose tolerance and insulin signaling." (PMID 38203217, 2023). "The accumulation of fat mass induces low-grade chronic inflammation by producing proinflammatory cytokines such as TNF-α, IL-6, and MCP-1 in adipose tissue, and obesity-induced inflammation induces insulin resistance in the liver and muscles." (PMID 38201252, 2023). "BAT deficiency induces obesity, whereas increased BAT levels regulate glucose homeostasis and improve insulin sensitivity." (PMID 37041517, 2023). "Obesity can impair insulin sensitivity by damaging insulin receptors and β-cell function in the pancreas." (PMID 37308493, 2023). "Obesity-induced IR is characterized by impaired insulin function that inhibits hepatic glucose output and promotes glucose uptake in adipose tissue and muscle." (PMID 37056675, 2023). "Traditional treatment of obesity includes a low-carbohydrate diet, drugs that increase insulin sensitivity, and incorporating physical exercise, all strategies to restore proper energy balance." (PMID 37237974, 2023). "To this end, we examined the effects of 12 weeks of HIFT supplemented with astaxanthin on body composition, cardio-respiratory fitness, adipokine levels, insulin resistance and lipid profiles in males with obesity." (PMID 36678157, 2023). "The depletion of PTEN in hepatocytes of mice significantly induces FGF21, improves muscle insulin sensitivity, and leads to decreased obesity, indicating a certain synergistic effect among the liver, muscle, and fat." (PMID 38069273, 2023).
Obesity (continued). "Obesity is closely related to IR, and most obese experimental animals showed impaired insulin response, while some experimental results demonstrated that FINS concentration in mice fed with a high-fat diet did not change significantly." (PMID 37034166, 2023). "Given the muscle GR–mediated enhancement of hyperinsulinemia in the CORT-induced obesity model, we next examined the plasma insulin levels of the ob/ob model." (PMID 36917179, 2023). "Pathway analysis revealed that hsa-miR-15b-5p and hsa-miR-223-3p are involved in numerous obesity-related functions, including the FoxO, insulin, Ras, and AMPK signaling pathways." (PMID 37904219, 2023). "Obesity can impair glycemic compensation not only through insulin resistance but also through disruption of beta-cell function due to adverse secretion of adipokines." (PMID 36717953, 2023). "PCOS adolescents with obesity have a 50% reduction in insulin sensitivity in peripheral tissues, hepatic IR, and increased levels of circulating insulin owing to its reduced clearance." (PMID 36980074, 2023). "Other factors found in human milk that are associated with infant growth and later obesity include human milk oligosaccharides (HMO), long-chain polyunsaturated fatty acids (LCPUFA), and hormones such as leptin, insulin, ghrelin, and adiponectin." (PMID 37475022, 2023). "A possible mechanism is that maternal overweight and obesity are related to the effects of oxidative stress, proinflammatory status, energy homeostasis, angiogenesis, and insulin insensitivity." (PMID 37106323, 2023). "The homolog of NUDT3 in Drosophila, Aps, is involved in insulin signaling, while defects in PACSIN1 have been associated with schizophrenia-like behavior in mice, another condition linked to obesity." (PMID 37620670, 2023). "Non-alcoholic fatty liver disease is caused by lifestyle-related diseases such as obesity and HTN, which reduce the amount of insulin produced in the liver and tend to accumulate visceral fat." (PMID 37762928, 2023). "High-energy diets, obesity and increased triglyceride and cholesterol deposition in hepatocytes result in hepatocyte ballooning and oxidative stress, insulin resistance, ROS release, FFA oxidation and FFA lipotoxicity." (PMID 37233716, 2023). "This leads to a cycle of weight gain and increased insulin requirements which, once set in motion, is difficult to change as obesity is likely to continue into adulthood especially in the T1D population." (PMID 37614408, 2023). "On the contrary, body weight loss and increased energy expenditure prevailed in transgenic mice expressing human FGF-19 and these mice furthermore presented a resistance to obesity and insulin desensitization." (PMID 37239098, 2023). "CTRP12 or adipolin is an insulin-sensitizing adipokine that is abundantly produced by AT and whose expression levels decrease in rodent models of obesity." (PMID 37251328, 2023). "In children with obesity, improved glycemic and lipid levels were accompanied by reduced insulin levels during OGTT after metformin treatment." (PMID 37623862, 2023). "Our study found that SIRT2 deficiency exacerbated hepatic steatosis, inflammation, and fibrosis, while also impairing insulin sensitivity and aggravating obesity." (PMID 37240315, 2023). "Obesity is one of the important reasons for insulin resistance/insufficient insulin secretion and increased blood glucose." (PMID 37064684, 2023). "Both oxidative stress and inflammation contribute to insulin resistance of the adipose tissue and other organs like the skeletal muscles, thereby promoting a diabetic status in patients with obesity." (PMID 38136564, 2023). "Taken together, these findings suggest that the healthcare for individuals in cluster 1 should focus on obesity reduction, with the aim of reducing insulin resistance and avoiding the decline in compensatory increased insulin secretion." (PMID 36769457, 2023).
Obesity (continued). "This is the first study comparing the maternal metabolome in the first trimester of pregnancy considering proxies of obesity (BMI) and adiposity (leptin) as well as of the glucose-insulin axis (glucose, C-peptide, ISHOMA)." (PMID 37029207, 2023). "Hereby, we demonstrate that both systemic and intracerebroventricular (ICV) administrations of SHLP2 protected the male mice from high-fat diet (HFD)-induced obesity and improved insulin sensitivity." (PMID 37468558, 2023). "Our enrichment analysis offers evidence of the complex interplay between key obesity genes and the brain, impacting feeding behavior, energy expenditure, metabolic homeostasis, and insulin secretion." (PMID 37620670, 2023). "Actually, we combined the influence of insulin sensitivity/secretions and obesity as GDM subtypes, which reflect the whole pathophysiological process leading to the elevated blood glucose during pregnancy." (PMID 36890429, 2023). "Amelioration of dyslipidemia status has been assumed to relate to improved insulin sensitivity and leptin modulation, as well as obesity prevention." (PMID 37571314, 2023). "To account for potential obesity heterogeneity, we also included parameters of the glucose-insulin axis (glucose, C-peptide and ISHOMA)." (PMID 37029207, 2023). "A relationship between insulin concentration was demonstrated in the overweight group of children compared to the obesity group." (PMID 37892696, 2023). "In mouse models of partial leptin deficiency, it was shown that a reduced leptin level counteracted diet-induced obesity, adipose tissue inflammation and enhanced insulin sensitivity and glucose tolerance." (PMID 38136564, 2023). "Consuming large amounts of added sugars and refined grains can contribute to developing resistance to insulin and overweight or obesity, both of which are hallmarks of metabolic syndrome." (PMID 38248733, 2023). "EDCs can promote obesity by stimulating adipo- and lipogenesis of target cells such as adipocytes and hepatocytes, disrupting glucose metabolism and insulin secretion, and impacting hormonal appetite/satiety regulation." (PMID 36674599, 2023). "GDM risk increases with maternal age due to age-related decline in insulin sensitivity, increased prevalence of obesity, and altered hormonal balance." (PMID 37546039, 2023). "The results show that the obesity model used is consistent with previous work because the HFD group presented higher fasting insulin values than the control group." (PMID 37237974, 2023). "Obesity, abdominal fat gain, lipid and lipoprotein disorders, impaired insulin, glucose homeostasis, systemic inflammation, as well as oxidative stress, have been associated with frequent fast-food consumption." (PMID 36900540, 2023). "Growing evidence indicates that fetal malnutrition, early exposure to endocrine-disrupting chemicals (EDC), and early exposure to EDC contribute to obesity, visceral fat accumulation, and insulin resistance." (PMID 37274345, 2023). "Recent studies have shown that endoplasmic reticulum stress and activation of the unfolded protein response (UPR) promotes obesity and insulin signaling disturbance." (PMID 37108282, 2023). "As obesity and metabolic derangements deteriorate and prediabetes progresses to overt T2D, defective β-cell insulin production becomes more and more pronounced." (PMID 37432389, 2023). "The paradigm states that metabolic stress from excessive nutrients initially causes beta-cell overstimulation, leading to primary hyperinsulinemia that precedes obesity and insulin resistance as secondary compensatory mechanisms." (PMID 37623862, 2023). "Overall, our results suggest this hormone, its receptors, and the signaling pathways it activates are robust potential targets for treatment in obesity and aging‐related disruption of glucose‐stimulated insulin secretion." (PMID 37060190, 2023).
Obesity (continued). "Studies have demonstrated that insulin and leptin resistance observed in individuals with obesity can alter the prefrontal function as well as the cognitive function that regulates food intake." (PMID 37261609, 2023). "In model systems and human studies, sustained decreases in AMPK activity induced by obesity or overnutrition accompany IR, whereas AMPK activation is associated with increased insulin sensitivity." (PMID 37898813, 2023). "In this study, LEP expression was found to be upregulated in PCOS patients with obesity and in GCs treated with insulin." (PMID 37562217, 2023). "Our work revealed that Hachimijiogan, a Japanese Kampo medicine, exerts metabolic effects in mice and prevented diet-induced obesity and modulated whole body insulin sensitivity." (PMID 37251332, 2023). "As cells that highly infiltrate into WAT during obesity, macrophages can affect insulin sensitivity and glucose homeostasis." (PMID 37876013, 2023). "For instance, a RCT of a culturally adapted 3- month intervention, offering 3 times weekly physical activity and nutrition education, significantly improved insulin sensitivity and weight-specific quality of life in youth with obesity." (PMID 38108040, 2023). "In this study, in order to evaluate the obesity status and the effect of treatment and pretreatment with different doses of garlic powder, the serum levels of insulin, glucose, and the HOMA-IR index were determined." (PMID 36644444, 2023). "Relationships between intraocular pressure andocular pulse amplitude measurements and age, sex, obesity, pubertal status,and insulin resistance were investigated." (PMID 35319649, 2023). "This review focuses on the effects of obesity, insulin dysregulation and hyperinsulinemia on the reproductive functions of mares and the implications on foal health before and after birth." (PMID 37152686, 2023). "In our work, the ethanolic extract of C. papaya was given to the investigational rats to overcome the obesity spurred inflammation and progress insulin sensitivity in the fatty tissues of high fat diet- streptozotocin-incited T2DM rats." (PMID 36826001, 2023). "In one report, the subjects with obesity were classified into two groups according to baseline insulin resistance measured using the clamp." (PMID 36902180, 2023). "While the anti-obesity drugs are anti-diabetic to some extent, some anti-diabetic medicines, however, have been shown to increase body weight, such as insulin." (PMID 37152942, 2023). "Increased lipolysis in insulin-resistant adipose tissue in the setting of obesity further exacerbates hepatic steatosis and highlights the importance of maintaining adipose insulin sensitivity and healthy adipocyte expansion in the setting of overnutrition." (PMID 36749637, 2023). "It modulates obesity markers such as glucose, INS, leptin, adiponectin, lipid profile, and liver enzymes." (PMID 37534085, 2023). "Adipose tissue macrophages and conventional dendritic cells (cDC) interact with adipocytes and can modulate adipogenesis, insulin sensitivity, and tissue remodeling in the setting of obesity, though there are few similar data in PWH." (PMID 37711619, 2023). "Obesity can also decrease adiponectin, an anti-inflammatory cytokine produced by adipocytes that improves insulin sensitivity." (PMID 38130527, 2023). "Obesity induces morphological changes, as well as pathological impairments, such as reduced insulin sensitivity." (PMID 37462619, 2023). "Adipose tissue macrophages (ATM) of mice with obesity can secrete exosomes transferring exosomes with miRNA into insulin target cells, which can evaluate FFA levels in the blood, damaging insulin sensitivity, and enhancing insulin resistance." (PMID 37791070, 2023). "The relationship between T2D and QoL is complex; changes in glycaemic control, insulin use and body weight are all likely to affect QoL in patients with T2D and obesity." (PMID 35869383, 2023).
Obesity (continued). "According to the carbohydrate–insulin model of obesity, the intake of high‐glycemic carbohydrates results in elevated postprandial insulin responses, which are believed to promote body fat accumulation, in turn increasing hunger and energy intake." (PMID 36695728, 2023). "Studies in mice show that deletion of Nlrp3 protects against HFD-induced obesity, IR, dyslipidemia as well as infiltration of macrophages into the AT, and leads to improved serum glucose and insulin levels and insulin signaling in liver and cardiac tissue." (PMID 37239938, 2023). "Such CORT-induced fat accumulation was alleviated by suppressing insulin production (streptozotocin injection), indicating that hyperinsulinemia enhanced by muscle GR signaling promotes obesity." (PMID 36917179, 2023). "Based on insulin and C-peptide levels, obesity, acanthosis nigricans, and family history of T2D, higher frequencies were found in the T2D group than in the T1D group in the present study." (PMID 36835954, 2023). "MEG3 has been found to maintain glucose homeostasis and insulin signaling by protecting the hepatic endothelium against cellular senescence in obesity." (PMID 36979495, 2023). "Our study investigated global insulin secretion and the two different phases of beta-cell response after oral glucose in children and adolescents with obesity and OSA." (PMID 36670156, 2023). "We demonstrate that GR has an important function in macrophages during obesity by limiting adipose tissue inflammation and lipolysis to promote insulin sensitivity." (PMID 37080971, 2023). "Part of this favourable effect is via prevention of obesity and also inhibition of ceramide biosynthesis and improvement in insulin action." (PMID 36894641, 2023). "Stress also induces secretion of both glucocorticoids, and insulin which in turn increases motivation for food, and promotes food intake and obesity, respectively." (PMID 36980058, 2023). "Estrogen receptors play a crucial role in regulating lipid accumulation and improving insulin sensitivity and are therefore regarded as therapeutic targets for preventing obesity and metabolic disorders." (PMID 37615638, 2023). "Its overexpression occurs in patients with obesity, inhibits insulin-stimulated glucose uptake in adipocytes, and negatively regulates gluconeogenesis in hepatocytes." (PMID 37373398, 2023). "It was demonstrated that the treatment with fucoidan from brown alga Undaria pinnatifida stimulated glucose uptake in normal 3T3 adipocytes and restored insulin-stimulated glucose uptake in obesity-induced insulin-resistant adipocytes." (PMID 37569428, 2023). "After six weeks, they showed apparent obesity, increased fasting blood glucose and insulin levels, and increased water intake and food intake." (PMID 37152933, 2023). "An age-dependent or obesity-induced increase in free fatty acid (FFA) levels is considered a likely mechanism causing changes in lipid metabolism through impaired insulin signaling." (PMID 38068822, 2023). "Animal studies show that the β-cells adapt to obesity by increasing glucose-stimulated insulin secretion (GSIS) and β-cell mass." (PMID 37134142, 2023). "Many factors contribute to overweight/obesity in T1DM which include longer duration of insulin treatment which induces weight gain and thereby increases peripheral IR, and sedentary lifestyles with contribution from increasing age." (PMID 38111445, 2023). "Here, we evaluated the role of PKN1 in glucose metabolism under insulin-resistant conditions in primary visceral adipose tissue (VAT) from 31 patients with obesity and in murine 3T3-L1 adipocytes." (PMID 37242297, 2023). "When asked about the effect of obesity on insulin sensitivity, the major proportion (67.30%) of participants correctly believed that obesity affects insulin sensitivity." (PMID 38054130, 2023).